IGF1R (insulin like growth factor 1 receptor)
Diseases named in the same sentence as IGF1R in open-access papers (continued):
Sharing a sentence is not in itself a finding about the gene and the disease.
colon carcinoma (continued). "With regard to the IGF/IGF-1R axis, treatment with EGCG showed decreased levels of IGF-1 and reduced IGF-1R activation, whereas the levels of IGFBP-3 were found to be increased in colon cancer cells." (PMID 28445390, 2017). "Western blotting confirmed the expression of IGF-1R in HT-29 and HCT 116 human colon cancer cell lines, both expressing green fluorescent protein (GFP)." (PMID 26731105, 2016). "Both HT-29-GFP and HCT 116-GFP colon cancer cell lines expressed pro-IGF-1R and IGF-1R, as determined with Western blotting." (PMID 26731105, 2016). "miR-497 is downregulated in colon cancer, which is capable of inhibiting cancer cell survival, proliferation, and invasion, by targeting IGF1R (insulin-like growth factor 1 receptor), an angiogenic activator that contributes to angiogenesis in tumors." (PMID 26064956, 2015). "IGF1R and KRAS targeting by let-7d-5p and 3p was further experimentally validated since the two miRNA species were differentially expressed in colon cancer cells in reverse directions: let-7d-5p was up-regulated whereas let-7d-3p was down-regulated." (PMID 25287248, 2014). "MK-2206 inhibits the phosphorylation of Akt at both Ser473 and Thr308 in two IGF1R-dependent GEO and CBS colon cancer cell lines." (PMID 24581231, 2014). "In this report, we present evidence that miR-497 has an important role in inhibiting IGF1-R expression and activation of PI3K/Akt signalling, and in suppressing proliferation, survival and invasive behaviour in human colon cancer cells." (PMID 22710713, 2013). "Growth factors and receptors FGF2, IGF1R, PDGFRB and TGFA were identified as factors contributing selectively to the control of U2OS osteosarcoma and HCT116 colon cancer cell growth." (PMID 24023735, 2013). "Introduction of this construct into HCT116 colon cancer cells showed that the reporter activity was suppressed, albeit moderately, by the presence of the 3′UTR of IGF1-R, relative to basal levels observed with the control vector." (PMID 22710713, 2013). "Remarkably, growth factors and receptors FGF2 and IGF1R were identified as common, and PDGFR and TGFA as specific factors contributing to U2OS human osteosarcoma and HCT116 colon cancer cells growth, respectively." (PMID 24023735, 2013). "We have previously shown that RSV suppressed IGF-1 signaling via suppression of IGF-1R resulting in G1 cell cycle arrest and suppression of proliferation in HT-29 and SW480 colon cancer cells." (PMID 21849056, 2011). "In our study, we attempted to answer how IGF1R inhibition modulates the effect of tumor-derived self-DNA on TLR9 signaling and autophagy response by examining the metabolic activity and proliferation of HT29 colon cancer cells." (PMID 35651701, 2022). "The inhibitory effect of BMS-754807 on colon cancer cell growth was stronger compared to the effect of linsitinib, and the anti-neoplastic effect was mostly independent of IGF1R." (PMID 36013453, 2022). "Meanwhile, treatment of colon cancer cells with curcumin or dasatinib induced significant reduction of p-EGFR while combination treatment led to much greater reduction of both p-EGFR and p-IGF-1R." (PMID 34867402, 2021). "Indeed, previous studies showed that suppression of IGF-1R decreases ABCC2 expression and promoted drug sensitivity in human colon cancer cells, and that IGF-1 increased the expression of ABCC1, ABCC2, and ABCC3 in both leukemia cells and ovarian cancer cells." (PMID 33291663, 2020). "We also found that p70S6K1 activation by IGF-1R inhibition is independent of K-Ras and PIK3CA mutations that frequently occur in colon cancer." (PMID 32843616, 2020). "Therefore, our data also provide a promising strategy of combining the IGF-1R and MEK1/2 inhibitors to suppress colon tumor growth." (PMID 32843616, 2020).
colon carcinoma (continued). "We also previously demonstrated that simvastatin increases the apoptosis of colon cancer cells and suppresses ERK and Akt via the downregulation of IGF-1R expression and proapoptotic ERK activation and might be beneficial for the treatment of colon cancer." (PMID 26966430, 2016). "Moreover, colon cancer-derived insulin-like growth factor-1 (IGF-1) increased Arg1 expression, and treatment with the IGF1R inhibitor AG1024 inhibited that increase." (PMID 27683110, 2016). "The present report suggests that fluorescence imaging with fluorophore-conjugated IGF-1R antibody could be combined with endoscopy and FGS for better diagnosis and treatment of colon cancer." (PMID 26731105, 2016). "The IGF-1R fluorescent-antibody labeled liver metastases were very bright compared to the normal liver and the fluorescent-antibody label co-located with green fluorescent protein (GFP) expression of the colon cancer cells." (PMID 26731105, 2016). "The IGF axis seems to play a critical role for the development of these, since colon cancer cells manipulated to express a dominant-negative IGF-1R failed to produce liver metastases although the malignant cells were injected directly into the organ." (PMID 22159423, 2012). "Tumor tissue extracted from 48 colon cancer patients significantly overexpressed IGF-1R and IGF-2 mRNA, but not IGF-1 mRNA." (PMID 22159423, 2012). "In order to establish the efficacy of resveratrol against IGF-1 induced colon cancer growth, we utilized HT-29 and SW480 (IGF-1R constitutively active) human colon cancer cell lines and treated them with/without IGF-1 and/or resveratrol." (PMID 20504360, 2010). "IGF-1R siRNA did not alter apoptosis suggesting that IGF-1R siRNA suppresses colon cancer cell growth primarily through anti-proliferative and/or senescence mechanisms." (PMID 20504360, 2010). "In colon cancer, curcumin combined with 5-fluorouracil (5-FU) and oxaliplatin (FOLFOX) were found to induce higher levels of apoptosis by reducing both the expression and activation of EGFR, IGF-1R, HER-2, and HER-3 by a greater magnitude then either agent alone." (PMID 34867402, 2021). "Our studies identify a novel crosstalk between TGFβ and IGF-1R signaling through the adaptor protein, IRS-1, indicating that one of the mechanisms by which TGFβ elicits its tumor suppressor function is through inhibition of IRS-1 expression and activation in colon cancer cells." (PMID 28414818, 2017). "Since in colon cancer metformin exerts an anti-proliferative effect by suppressing IGF-1R signaling, we next analyzed the activating phosphorylation pattern for Akt and extracellular signal-regulated kinases 1/2 (ERK1/2), the two main IGF-1R downstream pathways in H295R cells." (PMID 27391065, 2016). "However, while an IRS-1 resistant to miR-145 can rescue colon cancer cells from miR-145-induced growth inhibition, an IGF1R resistant to miR-145 failed to rescue colon cancer cells from growth inhibition." (PMID 25474488, 2014). "Since IGF1-R has an important role in mediating activation of the PI3K/Akt pathway, we focused on examining whether miR-497-triggered suppression of IGF1-R is reflected in regulation of PI3K/Akt signalling in colon cancer cells." (PMID 22710713, 2013). "However, the interrelated role of IGF1R inhibition and TLR9/autophagy signaling in HT29 colon cancer cells has not yet been clarified." (PMID 35651701, 2022).
diabetes (123 papers, 2011 to 2025). "GRB10-mediated inhibition of IR and IGF-1R activity is linked to cognitive impairments associated with diabetes in rodents." (PMID 40523800, 2025). "Nevertheless, a possible association between diabetes mellitus and IGF1R expression in HCC should be further investigated in future studies." (PMID 39775131, 2025). "Although IGF1R-expression was associated with diabetes mellitus at first, the association lost its significance after correction for multiple testing." (PMID 39775131, 2025). "In contrast, we cannot exclude the possibility that some IGF1R gain-of-function mutations are associated with diabetes as previous studies showed." (PMID 38274107, 2023). "In fact, the dysregulation of IGF1 and IGF1R levels has been described in association to hyperglycemia in diabetes, including T1DM, and several diabetic complications." (PMID 36506063, 2022). "The insulin-like growth factor 1 receptor (IGF-1R) plays an important role in regulating functional impairment associated with diabetes." (PMID 34663464, 2021). "FoxOs are critical mediators of insulin action on transcription in liver and have been shown to play a role in muscle atrophy associated with diabetes and loss of IR and IGF1R." (PMID 35185597, 2021). "Both obesity and diabetes are associated with dysregulation of both the IGF-1R and the RAGE (Receptor for Advanced Glycation End Products) pathways, which contribute to complications of these disorders." (PMID 33557316, 2021). "According to our results, during prolonged periods of starvation, a reduction of IGF1R signaling would cause an increase in insulin granule release, which is observed in the physiopathology of diabetes." (PMID 32934005, 2020). "The lncRNAs, directly or indirectly associated with IGF-1R, that have impact on diabetes and cancer pathogenesis are highlighted here." (PMID 31847392, 2019). "Igf1r represents another diabetes-associated gene, whose locus overlaps with six differentially expressed lncRNAs." (PMID 31278342, 2019). "We showed that insulin treatment is associated with higher IGF1R and p-mTOR tumor expression in women with diabetes." (PMID 29486734, 2018). "We found that insulin treatment in women with diabetes is associated with p-mTOR tumor expression, and in premenopausal women with IGF1R tumor expression." (PMID 29486734, 2018). "Insulin treatment was only associated with IGF1R expression in tumors of premenopausal women with diabetes." (PMID 29486734, 2018). "Increased Igf1R expression in adipose tissue is associated with reduced incidence of diabetes, because it promotes insulin signalling and therefore favours fat storage over ectopic energy storage." (PMID 28212289, 2017). "Growth factor receptor-bound protein 10 (Grb10), a suppressor of IGF1R pathway, has been shown to play a critical role in regulating diabetes-associated cognitive impairment." (PMID 25268761, 2014). "A large number of studies have demonstrated the existence of IR/IGF1R hybrid receptors, consisting of an αß subunit pair of the IR associated with an αß subunit pair of the IGF1R, in both normal and pathological situations, including diabetes and cancer." (PMID 22848683, 2012). "Consistent with this, although Insr knockout (KO) causes only mild diabetic symptoms with impaired insulin secretory function and total IR in β cells, Insr/Igf1r double KO causes overt diabetes associated with reduced β cell mass, increased apoptosis and severely compromised β cell function." (PMID 38418586, 2024). "IGF-1R is associated with greater tumor aggressiveness in PCa patients with diabetes." (PMID 36831629, 2023). "Interestingly, knockout of miR-375 in mice model revealed insulin resistance and decreased glucose homeostasis, leading to diabetes, an effect that was associated with upregulation of IGF1R." (PMID 38274107, 2023).
diabetes (continued). "Clinically, insulin resistance and altered IR signaling is linked to diseases such as diabetes, accelerated atherosclerosis, and fatty liver disease, whereas IGF1R mutations or IGF-1 deficiency cause pre- and postnatal growth retardation and specific defects in tissue growth, e.g., microcephaly." (PMID 36548088, 2023). "Understanding the role of IGF-1R signaling in these processes may also contribute to the development of new strategies for combination therapy in diabetes, colitis and colitis-associated CRC." (PMID 36835075, 2023). "The significant association between IGF1R expression and diabetes is evident." (PMID 38274107, 2023). "However, deregulation of IGF1R expression, commonly seen within individuals in their late-life stage, is associated with the occurrence and development of diabetes, inflammation and cancer." (PMID 32674072, 2020). "Diabetes and obesity are also associated with HS, implicating IGF1R." (PMID 31608281, 2019). "Among women with diabetes, insulin use (n = 53) was significantly associated with higher tumor protein expression of IGF1R (OR = 2.36; 95%CI:1.02–5.52; p = 0.04) and p-mTOR (OR = 2.35; 95%CI:1.13–4.88; p = 0.02), especially among women treated with insulin analogues." (PMID 29486734, 2018). "Obese patients have been shown to have higher circulating levels of IGF-1 than non-obese patients in the presence of hyperinsulinemia, and animal studies have revealed that insulin resistance and activation of the IGF/IGF-1R axis are implicated in obesity- and diabetes-related liver carcinogenesis." (PMID 25789501, 2015). "Down-regulation of GIGYF2 expression may provide a potential novel approach to treat diabetes-associated cognitive impairment caused by aberrant IGF1R signaling pathway." (PMID 25268761, 2014). "Mutations in the IGF1R gene, which encodes the insulin-like growth factor 1 receptor, could potentially disrupt insulin signaling and glucose metabolism, contributing to diseases like diabetes or cancer." (PMID 38737102, 2024). "Menopause seemed to modify the association between insulin and IGF1R expression (p = 0.07) and the difference in IGF1R expression between tumors of insulin and non-insulin users was only observed among premenopausal women with diabetes (OR = 5.10; 95%CI:1.36–19.14; p = 0.02)." (PMID 29486734, 2018). "Therefore, down-regulation of GIGYF2 expression may provide a potential novel approach to treat diabetes-associated cognitive impairment caused by aberrant IGF1R signaling pathway." (PMID 25268761, 2014). "Patients who suffer from type 2 diabetes mellitus (DM) are at increased risk of developing AD and AD patients show decreased insulin-IGF-1R signalling." (PMID 25025689, 2014). "c-IGF1R high was associated with AFP positivity (p = 0.037) and the diagnosis of diabetes mellitus (p = 0.034)." (PMID 39775131, 2025). "Blocking Igf1r in β-cells can mitigate aging-induced β-cell senescence and dysfunction, which contribute to a diabetes-related decline in β-cell function." (PMID 40556865, 2025). "Studies on mouse models explored cognitive impairment as a complication of diabetes through the repression of IGF-1R by GIGYF2." (PMID 40523800, 2025). "IGF-1 induced acromegaly-like side effects in clinical trials as a diabetes therapy, and more importantly is a mechanistically distinct intervention from IGF-1R over-expression." (PMID 40171617, 2025). "RT‐qPCR detection shows that overexpression of circ‐IGF1R decreased miR‐503‐5p expression more than HEV treatment ulcerated tissue in mice with diabetes." (PMID 38984951, 2024). "Circ‐IGF1R upregulation increased the therapeutic effect of ADSC‐HEV on wound healing in mice with diabetes." (PMID 38984951, 2024).
diabetes (continued). "Immunohistochemicals for Tunel staining show that overexpression of circ‐IGF1R increased the protective effect of HEV in decreased apoptosis in ulcerated tissue in mice with diabetes." (PMID 38984951, 2024). "While IGF-1R activity is involved in diabetes, a pathology affecting the whole organism, once more the involvement of IGF-1R pathways appears to be tissue-dependent." (PMID 39638246, 2024). "Overexpression of circ‐IGF1R increased the protective effect of HEV on the promotion of wound healing in mice with diabetes." (PMID 38984951, 2024). "The in vivo experiment detection shows that overexpression of circ‐IGF1R increased the protective effect of HEV on promoting wound healing in mice with diabetes." (PMID 38984951, 2024). "We also investigated the correlation between mRNA targeted by miRNA biomarkers in IRS-related events by the IGF1R pathway and clinical indicators related to diabetes in a publicly available BxD mouse database." (PMID 37608331, 2023). "Peripherally, IGF-1 increases glucose uptake and functional inactivation of IGF1R in skeletal muscles of mice, resulting in insulin resistance and diabetes." (PMID 37654561, 2023). "Noncoding RNAs (LncRNA and Micro RNAs) have a major role in disease development, including diabetes and cancer, through the regulation of IGF1R or other IGF signaling molecules." (PMID 38274107, 2023). "Here we demonstrate significant up-regulation of Type 2 diabetes mellitus pathways in H1299IR cells through overexpression of IGF-1R and down-regulation of the PI3K/Akt signaling pathway." (PMID 36769365, 2023). "Efforts to develop small molecule modulators the IR and IGF1R have focussed on identifying IGF1R antagonists and IR agonists, owed to the receptors' respective roles cancer and diabetes." (PMID 35647546, 2022). "Drugs/inhibitors or molecules targeting the IGF-1/IGF-1R signaling axis which affect diabetes and intraocular malignancy." (PMID 36003786, 2022). "Of note, we showed that the MAO-dependent regulation of these miRNAs in diabetes impacts the activation of the IGF1R/PI3K/AKT axis." (PMID 36078109, 2022). "Combining with the current status of diabetes research, we want to investigate the reasons for IGF-1R inhibition of osteogenic differentiation of PDLSCs in high glucose environment." (PMID 34663464, 2021). "FoxOs are critical mediators of diabetes-related muscle atrophy downstream of IR/IGF1R, and control muscle mass via regulation of ubiquitin-proteasome and autophagy-lysosome pathways." (PMID 35185597, 2021). "Diabetes during pregnancy strongly influences the regulation of both insulin-like growth factor-1 receptor (IGF-1R) and insulin receptor (InsR) in the rat hippocampus." (PMID 34417446, 2021). "Further studies are necessary to better understand the role of IR and IGF-1R in physiological pregnancies, particularly those complicated by diabetes." (PMID 33776919, 2021). "For example, GH therapy should be performed carefully in patient 5 with IGF1R abnormality and patient 6 with SHORT syndrome, due to insulin resistance and a high risk of developing diabetes mellitus." (PMID 32546215, 2020). "In this study, we demonstrated that DM‐induced hypermethylation suppressed IR and IGF1R expression, which in turn inhibited the progression of diabetes by suppressing mast cell activation and airway responsiveness." (PMID 33145961, 2020). "Collateral activation of IGF1R is a key concern in the use of insulin or insulin analogs for the treatment of diabetes." (PMID 31378829, 2020). "Dysregulation of IGF-1R results in many diseases, including cancers, thyroid eye disease, psoriasis, and diabetes." (PMID 32605985, 2020). "Collectively, our results demonstrate that inhibition of calpain regulated VSMC phenotypic switch via miR-223/IGF-1R/AMPK signaling axis, supporting the potential application of calpeptin on platelet-associated vascular disease in diabetes." (PMID 32733269, 2020).